TRAJ56 (T cell receptor alpha joining 56)
Gene: T-cell receptor joining (J) gene on chromosome 14 (22,479,521 to 22,479,582, forward strand). Ensembl gene ENSG00000211835.
Diseases named in the same sentence as TRAJ56 in open-access papers:
TRAJ56 is named in the same sentence as 2 diseases in open-access papers, as found by Europe PMC text mining. Sharing a sentence is not in itself a finding about the gene and the disease.
TRAJ56 shares sentences with these, for which no sentence is quoted: cancer (1 paper); gastric cancer (1).